IL1B (interleukin 1 beta)
Diseases named in the same sentence as IL1B in open-access papers (continued):
Sharing a sentence is not in itself a finding about the gene and the disease.
tumor (continued). "Higher concentrations of TCM were expected to result in higher IL-1β production in BMDMs because higher TCM concentration means that there are many tumor-secreted factors in the media." (PMID 30586442, 2018). "By contrast, with tumor progression, tumor-associated macrophages and MDSCs are enriched in TME, acting as endless suppliers of IL-1β, IL-23, and transforming growth factor beta (TGF-β)." (PMID 29997627, 2018). "It is also unclear which mechanisms of IL-1β production in TAMs are activated by tumor-secreted factors in the tumor microenvironment." (PMID 30586442, 2018). "In experimental studies, NLRP3 and thereby IL-1β expression levels were correlated with the tumor size and the metastatic status of the sentinel lymph node." (PMID 30042333, 2018). "In MC-38 tumor models, we demonstrated that TgMGLL stimulated the expression of proinflammatory cytokines (IL-1β and TNFα) and reduced the levels of anti-inflammatory cytokines (IL-10, Arg-1, and TGFβ) in a CB2-dependent manner in TAMs." (PMID 29968710, 2018). "We found that NLRP3 was aberrantly overexpressed in OSCC cells, and the abnormal expression was correlated with the tumor stage, lymph node metastatic status and IL-1β expression level." (PMID 29716544, 2018). "2-DG inoculation also attenuated the increased expression levels of NLRP3, caspase-1 p45, and IL-1β p31 in tumor-metastasized lungs." (PMID 30586442, 2018). "In this case, canonical Notch signaling directly regulates the expression of CCL2 and IL-1β, leading to the adhesion of monocytes to blood vessel and extravasation to migrate toward tumor tissue." (PMID 29686671, 2018). "It was shown that microenvironmental IL-1β leads to in vivo angiogenesis and invasiveness of different tumor cells." (PMID 30042333, 2018). "IL-1 signaling (Anakinra), and more specifically IL-1β (antibody-mediated) inhibition hereby seem to target key components of tumor development in most cases resulting in reduced tumor development." (PMID 30042333, 2018). "Pro-inflammatory cytokines such as IL-6, IL-1β and TNF are produced by a variety of cell types in a cancer including the tumor cells themselves, cancer-associated fibroblasts, and tumor-associated macrophages." (PMID 29883385, 2018). "Pro-inflammatory cytokines, such as TNF-α, IL-1β, and IL-6, contribute to the induction of tumor development by enhancing cancer stemness." (PMID 30486830, 2018). "The knockdown of NLRP-1 resulted in reduced IL-1β production and secretion, which led to the reduction of tumor proliferation in vivo and in vitro." (PMID 30149677, 2018). "An elegant study by the Reedijk group showed that Notch signaling in tumor cells regulates the expression of pro-inflammatory cytokines, IL1β and CCL2, and induced the recruitment of TAM." (PMID 29915603, 2018). "The cells produced cytokines such as IL-1B, IL-2, and IL-8 and displayed significant tumor-killing capacity." (PMID 29707004, 2018). "IL-1β, which is secreted by pro-inflammatory macrophages, activates NFκB signaling within tumor cells which, among other effects, upregulates IL-6 production thereby establishing a positive regulatory feedback loop for maintaining cells in a stem-like state." (PMID 29883385, 2018). "This was correlated with a higher production of pro-inflammatory TNF-α, IL-1β, and IL-6 cytokines and a stronger stimulatory effect on tumor growth achieved by these activated macrophages as compared with controls." (PMID 29435437, 2018). "Consistently, we detected a high IL-1β expression level in PCa tumor tissues obtained from mice suffering castration." (PMID 30257726, 2018). "Interleukin (IL)-1 is a group of potent proinflammatory cytokines including IL-1B which is activated by caspase-1 upon inflammasome activation in tumor cells." (PMID 30563955, 2018). "In basal-like breast cancer, tumor cells secrete both CCL2 and IL-1β in a Notch-dependent manner, and the secreted cytokine/chemokines, in turn, recruit monocytes to the tumor site." (PMID 29686671, 2018).
tumor (continued). "Taken together, these findings suggest that transduced inflammatory MSCs work as a major source of IL-1β in tumor microenvironment and initiate the formation of prostemness niche via regulating their secretome in an IL-1β-dependent manner." (PMID 29670904, 2018). "Here, the authors show that KRAS-mutant tumor cells require IKKα, activated via host-provided IL-1β, to promote MPE development and that co-inhibition of both KRAS and IKKα ameliorates the development of MPE in mouse models." (PMID 29445180, 2018). "The pro-inflammatory cytokines, i.e. tumor necrosis factor-α (TNF-α), interleukin-1β (IL-1β), and IL-6, activate inflammation, as proposed for the deterioration of angiogenesis in tumor cells." (PMID 30479366, 2018). "Caspase-1 can activate the pro-inflammatory cytokines IL-1β and IL-18, and promote inflammation and the formation of the tumor microenvironment, thus potentially promoting tumor infiltration and metastasis." (PMID 29626935, 2018). "IKKα is further shown to critically mediate IL-1β signaling in KRAS-mutant tumor cells, culminating in marked MPE-promoting effects delivered by C-X-C chemokine motif ligand 1 (CXCL1), and in oncogenic addiction with mutant KRAS evident as drug resistance." (PMID 29445180, 2018). "Macrophages of properdin-deficient mice have reduced M1 phenotype (IL-1β) and an increased production in the M2 phenotype (arginase-1, MCP-1, and IL-10) associated with tumour-promoting activity." (PMID 29483907, 2018). "Obvious expression of NLRP3 and IL-1β was found in the paraffin-embedded OSCC tissues, and the NLRP3 expression levels were correlated with the tumor size, lymphonode metastatic status and IL-1β expression." (PMID 29716544, 2018). "Activation of TLR4 in tumor cells promotes the synthesis of NFκB target genes, including IL-6 and IL1β, which results in resistance of tumor cells against cytotoxic lymphocytes." (PMID 29679017, 2018). "When administered to TLR4-expressing DC in vitro, HMGB1 augments the expression of pro-IL-1β and prevents the lysosomal degradation of engulfed tumor antigens, which is a major prerequisite for efficient cross-presentation." (PMID 29462947, 2018). "In oral squamous cell carcinoma (OSCC), TAMs were recruited by IL-1β-mediated upregulation of CXCR4 and CXCL1 and were associated with tumor migration, invasion and angiogenesis." (PMID 29976244, 2018). "The necessity of IL-1β for angiogenesis and invasiveness of the tumor in vivo was also verified in DA/3 mammary and prostate cancer cell models." (PMID 30042333, 2018). "In agreement, anti-tumor chemotherapeutics are most efficient when they induce immunogenic tumor cell death, accompanied by IL-1β induction in immune cells." (PMID 29983861, 2018). "This interaction leads to adipocytes with an activated, tumor supportive phenotype characterized by lipolysis, a decrease in adipocyte markers and an overexpression of pro-inflammatory cytokines like IL-6 and IL-1β." (PMID 29930291, 2018). "Several tumor-derived factors, among which CSF3, IL-1β, and IL-6, have been implicated in recruitment, activation, and expansion of MDSCs." (PMID 29675018, 2018). "One of the different modalities of neoplasm enhancement is achieved via releasing cytokines, such as IL1-β, IL-17, and IL-23 by the tumor inflammatory environment, as well as the tumor cells." (PMID 30544974, 2018). "This review article aims to summarize our current knowledge on the different layers of regulation of IL-1β expression, and the multi-facetted biological roles of this important cytokine under pathophysiological conditions with a focus on tumor development." (PMID 30042333, 2018). "IL-1β secreted from microenvironment or the malignant cells enhanced the tumor angiogenesis and invasiveness." (PMID 30174788, 2018).
tumor (continued). "Tumor-associated macrophage infiltration is associated with poor prognosis and sustains a cytokine milieu abounding of TGF-β, IL-1β, and CCL2 that collaborate to promote monocytes recruitment and promotes an immunosuppressive TME." (PMID 30154786, 2018). "Serum analyses revealed decreased levels of IL-1b and GM-CSF in animals 24 days after tumor cell inoculation in the anti-C1-IA group when compared to controls." (PMID 30647842, 2018). "Another important aspect of tumor growth being modulated and influenced by IL-1β knockout is the development of metastasis." (PMID 30042333, 2018). "Further studies in Il1b-deficent mice have shown an impairment of the potent IL-1β-mediated inflammation limiting tumor development." (PMID 30619282, 2018). "Another study, however, showed that chemotherapeutic treatment with an additional IL-1β inhibitor also reduced tumor growth, but increased metastasis." (PMID 30042333, 2018). "A recent report demonstrated that PDT-generated tumor cell lysate induces IL-1α, IL-1β, and IL-6 secretion from DCs suggesting that PDT-induced immune enhancement is due to DCs activation." (PMID 30680248, 2018). "Tumor-associated macrophages (TAM) are key effectors in cancer-related inflammation and reportedly, activated macrophages secrete IL-1β resulting in the activation of NF-κB signaling favoring tumorigenic progression." (PMID 30619282, 2018). "In a human oral squamous cell carcinoma (OSCC) model NLRP3 expression levels correlated with tumor size, lymph node metastatic status and IL-1β expression." (PMID 30042333, 2018). "In these pre-metastatic niches, factors are produced to attract and later on arrest tumor cells such as IL-1β, prokineticin 2, and MMPs while neighboring cells are stimulated to secrete VEGF to facilitate the arrival of tumor cells." (PMID 30233579, 2018). "IL-1β levels were increased in tumor-bearing mice, and the inhibition of glucose attenuated IL-1β levels in tumor-bearing mice." (PMID 30586442, 2018). "The impact of inflammatory milieu is supported by evidence that high intratumoral IL1-β and TNF-α were associated with poor response to neoadjuvant therapy, and high IL-8 and GM-CSF were predictive of tumor grade and size." (PMID 30567335, 2018). "A mouse CRC model shows IL-1B arising from tumor-infiltrating neutrophils plays an pivotal role in tumorigenesis." (PMID 30563955, 2018). "We showed that select inflammation and tumor-burden biomarkers (TNFα, IL-1b, IL-12, and CYFRA 21-1) and baseline neutrophil count were associated with patient outcomes in univariate analysis." (PMID 29398577, 2018). "Tumor infiltrating macrophages and neutrophils are also found to be dominant sources of IL-1β in TME, and treatments with IL-1β receptor antagonist lead to the delay of tumor formation." (PMID 29670904, 2018). "IL-1B induces a host of growth factors and angiogenic factors and promote tumor growth and metastasis." (PMID 30563955, 2018). "Some of the inflammatory mediators that were found elevated in the lungs of tumor-free IkkβΔmye animals also showed a trend towards slightly increased expression in the mammary glands of tumor-free IkkβΔmye animals and Il1b expression was significantly higher." (PMID 29682184, 2018). "Overall, latest data suggest that (additional) IL-1β inhibition in numerous tumor models is a promising therapeutic option." (PMID 30042333, 2018). "Increased levels of IL-1β in body fluids are correlated in experimental tumor models and in cancer patients with bad prognosis, carcinogenesis and invasiveness of the tumor." (PMID 30042333, 2018). "Further study showed that after blocking the effect of inflammasome activation by administration of YVAD‐CMK in vivo, the levels of capase‐1 and IL‐1β remarkably were reduced in tumour." (PMID 30160343, 2018). "Therapeutic concentrations of MTX abolish the effects of PDGF and IL-1β on tumor suppressor expression and inhibit mitogen-promoted FLS proliferation." (PMID 29554943, 2018).
tumor (continued). "These transformed neoplastic cells consequently produce inflammatory mediators including TNFα and IL1β that form a closed paracrine loop to perpetuate this tumor-reactive microenvironment." (PMID 29594035, 2018). "Confirming these results, IL-1β secreting tumors showed enhanced tumor angiogenesis as evidenced by highly increased secretion of VEGF by malignant cells and blood vessel density in tumors." (PMID 30042333, 2018). "PPARγ repression in pancreatic cancer cells results in the constitutive production of pro-inflammatory cytokines, including TNFα, IL-6, and IL-1β, relevant in the recruitment of macrophages and neutrophils into the tumor site." (PMID 30154786, 2018). "Altogether, IL-1β plays a major role already in the transition of chronic inflammation to tumor induction." (PMID 30042333, 2018). "The presence of cytokines in the ACP tumours was also assessed by multiplex ELISA against IL1B, IL6, IL8 (CXCL8), IL10, IL18, TNF (TNFα) and IFNG (IFNγ), which revealed the expression of all of these but IFNG in protein lysates from eight human ACPs." (PMID 29541918, 2018). "Inflammation induced through microbial or danger signals affects all stages of tumor development and the pro-inflammatory cytokines, IL-1β and IL-6, are important mediators for inflammation-induced tumorigenesis." (PMID 30447690, 2018). "Of these, interleukin‐1β (IL‐1β) showed age‐dependent upregulation in control lungs and tumors from old mice, whereas tumor‐specific upregulation was observed for Ccl7, IL‐15ra, and Cxcr6 cytokines in old mice." (PMID 29047229, 2018). "IL-1β, a well-documented proinflammatory cytokine, is suggested to be highly relevant with the inflammatory setup in several tumor types and is correlated with higher ratio of relapse and disease progression." (PMID 29670904, 2018). "The NLRP3 expression in OSCC tissues was positively correlated with tumor size, lymphonode metastasis status and IL-1β expression (product of the activated NLRP3 inflammsome)." (PMID 29716544, 2018). "As the nature of our model only allowed us to examine the innate immune system, further studies are needed to evaluate the role of IL-1β on the adaptive immune response and tumour growth in the context of TLR + bortezomib combination treatment." (PMID 29415982, 2018). "Consistent with murine bone-marrow-derived macrophages (BMDMs) and tumor cells, inhibition of glycolysis in LPS-activated macrophages significantly reduced the production of IL-1β." (PMID 29422900, 2018). "FLX-treated mice had a significantly lower level of serum IL-1β compared to untreated tumour mice (P = 0.022)." (PMID 28120908, 2017). "The treatment of tumor-bearing mice with NGF resulted in a reduction of tumor volume by 72%, increased lymphocytic infiltration of the tumor tissue, elevated levels of serum IL-1β and TNF-α and an increase in the activities of both SDH and LDH in EAC cells." (PMID 28878143, 2017). "Together these results revealed that TGF-β-type cytokines cooperate with TNF and IL-1β cytokines in the stimulation of MMP9 expression in tumor cells." (PMID 28423685, 2017). "Already early investigations demonstrated the link between secretion of IL-1β at the site of gastric carcinoma tissue and activation of NF-κB in the tumor." (PMID 28350359, 2017). "Sh-control-Th9 cells differentiated in the presence of IL-1β harboured a strong anti-tumour effect, which was completely lost when cells were infected with Sh-Irf8." (PMID 29233972, 2017). "Interlenkin-1β (IL-1β) is a member of proinflammatory cytokine family which are produced by both tumor cells and stromal cells." (PMID 28035062, 2017). "Cell sorting and transcriptome analysis of TAMs from both tumor entities revealed reduced expression of the inflammasome component Nlrp3 in S1PR1-deficient TAMs, which correlated with decreased IL-1β levels in tumor tissue." (PMID 28804221, 2017).
tumor (continued). "Studies have shown that IL-1β induces gastric cancer in mice through translocation of the H+/K+ ATPase-IFN-γ gene, and that IFN-γ is associated with tumor occurrence and autophagy." (PMID 28753959, 2017). "IL-1β transgenic mouse is widely used for testing the efficacy of anti- IL-1β therapies in cancer prevention and function of MDSCs in tumor microenvironment." (PMID 27713138, 2017). "Treatment of macrophages with caspase-1 inhibitor reduced secreted IL-1β production by a mean of 73% and concomitantly reduced tumour cell adhesion to levels obtained with resting macrophages." (PMID 28551814, 2017). "Previous studies have shown that in tumor-bearing mice, multiple inflammatory mediators, including interleukin-1β (IL-1β), IL-6, and prostaglandin E2 (PEG2), produced by tumor cells induce the accumulation of MDSCs in the tumor microenvironment of bone marrow." (PMID 29234328, 2017). "Recent findings highlight a rather underappreciated role of S1P in tumor lymphangiogenesis, referring to the production of interleukin-1β (IL-1β) and lipocalin-2 (LCN2) by a tumor-promoting macrophage phenotype." (PMID 28804221, 2017). "We have recently reported that Th9 cells have improved anti-tumour properties when differentiated in the presence of IL-1β." (PMID 29233972, 2017). "First, we showed that CR-LAAO induced the release of significant levels of IL-6 and IL-1β after 6 h of stimulation of HL-60 and HepG2 tumor cells." (PMID 28205610, 2017). "IL1-β activates immune cells such as macrophages at the treated tumor site, therefore supporting tumor regrowth and metastasis." (PMID 28147314, 2017). "Inhibition of the constitutively active Jak/STAT3 in gastric tumor leads to reduced polymorphonuclear inflammation and inhibition of pro-inflammatory cytokines IL-11, IL-6 and IL-1β and reduction of tumor volume in mice." (PMID 28350359, 2017). "We established the OSCC xenograft mouse model with WSU-HN6 and CAL27 cells and found that 5-FU treatment significantly limited OSCC growth and obviously increased the expression of NLRP3 and IL-1β in tumor cells." (PMID 28637493, 2017). "Active IL-1β and IL-18 can regulate the differentiation of tumor and T helper (Th) cells through downstream signal molecules including NFκB and IL-6." (PMID 29312552, 2017). "It is well known that pro-tumorigenic microenvironment inflammatory factors (such as IL-6, IL-1β) can promote tumor progression and remarkably impede therapy responses." (PMID 28881683, 2017). "Strikingly, efficacious tumour immunosurveillance due to tumour-specific CD4 + T cells was consistently related to increased local concentrations of both proinflammatory (IL-6, IL-1α, and IL-1β) and Th1-associated cytokines (IL-2, IL-12, and IFN-γ)." (PMID 29089667, 2017). "Together suggest that at least in culture, after recruiting MSCs to the vicinity of tumor cells, IL-1β secreted by IRISOE TNBC tumor cells through IL-1R activation, it activates AKT, ERK, and NF-κB signaling within these naïve MSCs." (PMID 29262555, 2017). "The elevated production of IL-10 by IL-1β-induced MDSCs and down-regulated production of IL-12 converted tumor immunity from a tumor-rejecting type 1 response to a tumor-promoting type 2 response, which promotes tumor growth." (PMID 29029545, 2017). "In response to different stimuli including IL-6, TGFβ, CCL20, IL-23, IL-1β, and so on, especially under cancer microenvironments, Th17 cells can mediate tumor regression or tumor promotion." (PMID 29379802, 2017). "Together suggest that IL-1β secreted by IRISOE tumor cells recruits MSC into tumors’ aggressiveness niche, activates them to secrete CXCL1, which entrains IRISOE tumor cells to secrete higher local and systemic levels of CCL2 and VEGF, in vivo." (PMID 29262555, 2017). "SDF-1α and TGF-β1 are involved in promoting tumor growth, whereas proinflammatory cytokines, such as Il-1β and TNF-α are mainly produced by classically activated (M1 polarized) tumor-associated microglia/macrophages." (PMID 28415741, 2017).